IRF4 (interferon regulatory factor 4)
Diseases named in the same sentence as IRF4 in open-access papers (continued):
Sharing a sentence is not in itself a finding about the gene and the disease.
parasitic infection (3 papers, 2015 to 2024). "While the precise role of IRF4 in the differentiation and function of MDSCs during schistosomiasis, particularly the disease caused by S. japonicum, remains understudied, intriguing parallels can be drawn from other experimental models of parasitic infections." (PMID 39609883, 2024). "Given the essential role of IRF4 in DC2 differentiation and function, we hypothesized that IRF4 KO mice would likely exhibit altered immune responses during schistosomiasis, particularly affecting Th2-mediated inflammation, which is a hallmark of this parasitic disease." (PMID 39609883, 2024). "Overall, these findings highlight the importance of IRF4 in regulating MDSCs and their impact on tissue damage during S. japonicum infection, providing valuable insights into potential therapeutic targets for managing the pathological consequences of this parasitic infection." (PMID 39609883, 2024). "In a Leishmania infection model, knockout of the IRF4 gene in DCs can significantly reduce parasitic infection and upregulate IFN-γ and IL-12, suggesting that the IRF4 of DCs may inhibit the Th1 responses induced by Leishmania33." (PMID 28240301, 2017).
psoriasis (3 papers, 2020 to 2021). An autoimmune condition characterized by red, well-delineated plaques with silvery scales that are usually on the extensor surfaces and scalp. "Congenital IRF5 deficiency induces the upregulation of IRF4 in DCs followed by an augmented IL-23 production from DCs, resulting in the amplification of Th17 responses and the exacerbation of imiquimod-induced psoriasis-like skin inflammation." (PMID 32456211, 2020). "Taken together, our results suggest that IRF5 deficiency induces the upregulation of IRF4 in DCs followed by augmented IL-23 production, resulting in the amplification of Th17 responses and the exacerbation of imiquimod-induced psoriasis-like skin inflammation." (PMID 32456211, 2020). "Consistently, in lesional skin of psoriasis, IRF4 is expressed in dermal infiltrating cells including dermal conventional type 2 DCs and the expression levels are elevated compared to healthy skin." (PMID 32456211, 2020). "Across five patients with psoriasis, we reported a sub-cluster of DCs (IRF4+ cDC2) that displays elevated expression of CCL17, CCL22, and IL12B, markers of cDC2s that have recently been shown to drive psoriatic inflammation in mice and humans through the recruitment of inflammatory T cells." (PMID 33053333, 2020). "In conclusion, our results demonstrate that both IRF5 and IRF4 may have an important role in the pathophysiology of psoriasis." (PMID 32456211, 2020). "The regulation of IRF4 or IRF5 expression may be a novel therapeutic approach to psoriasis." (PMID 32456211, 2020). "Besides, IRF4+ cDC2 cluster that displays an elevated expression of CCL17, CCL22, and a population of fibroblasts that expressed CCL19 and BAFF were reported in psoriasis biopsies." (PMID 34777377, 2021).
T-cell leukemia (3 papers, 2013 to 2022). A malignant disease of the T-lymphocytes in the bone marrow, thymus, and/or blood. "IRF4 was also named “multiple myeloma oncogene 1 (MUM1)” and “interferon consensus sequence-binding protein in adult T-cell leukemia cell lines or activated T cells (ICSAT)” in the context of cancers." (PMID 36077849, 2022).
agammaglobulinemia (2 papers, 2023). A decreased level of serum immunoglobulins. "More recently, two novel IRF4 disease-causing mechanisms have been described due to the characterization of IEI patients presenting with cellular immunodeficiency associated with agammaglobulinemia." (PMID 37809068, 2023).
autoimmune uveitis (2 papers, 2021). An autoimmune form of uveitis (disease). "Functional studies are necessary to further research this interesting topic in the future, like it was recently done in a study on murine interferon regulatory factor-4 (IRF4) depleted CD4+ T cells of an experimental autoimmune uveitis model (EAU)." (PMID 34385998, 2021). "Here, a connection between knockout of IRF4 and lower mitochondrial respiration in basal state in CD4+ T cells and suppressed autoimmune uveitis could be shown." (PMID 34385998, 2021).
bronchopulmonary dysplasia (2 papers, 2024). Bronchopulmonary dysplasia is a chronic respiratory disease that results from complications related to lung injury during the treatment of infant acute respiratory distress syndrome in low-birth-weight premature infants or from abnormal lung development in older infants. "Bronchopulmonary dysplasia (BPD) is characterized by alveolar dysplasia, and evidence indicates that interferon regulatory factor 4 (IRF4) is involved in the pathogenesis of various inflammatory lung diseases." (PMID 38491484, 2024).
cholangiocarcinoma (2 papers, 2023 to 2025). A carcinoma that arises from the intrahepatic biliary tree (intrahepatic cholangiocarcinoma) or from the junction, or adjacent to the junction, of the right and left hepatic ducts (hilar cholangiocarcinoma). "In cholangiocarcinoma, IRF4 promotes cancer proliferation as well as metastasis by regulating PI3K/AKT signaling." (PMID 37491232, 2023).
chronic kidney disease (2 papers, 2023 to 2025). Impairment of the renal function secondary to chronic kidney damage persisting for three or more months. "Previous studies have reported that Irf4 restricts chronic kidney disease progression and kidney fibrosis following ischemia reperfusion injury, potentially by enabling M2 macrophage polarization and suppressing a Th1 cytokine response." (PMID 41007655, 2025). "However, the data on the relationship between IRF1 or IRF4 and chronic kidney disease mainly come from murine studies, and conclusions on the clinical significance of IRF1 and IRF4 for chronic kidney disease should be elucidated in future studies." (PMID 37508555, 2023). "Furthermore, in a murine model of ischemia-reperfusion injury proceeding toward chronic kidney disease, an increased expression of IRF4 was detected, suggesting the regulatory role of IRF4 in the chronic phase." (PMID 37508555, 2023).
co-infection (2 papers, 2014 to 2020). "Conversely, the co-infection of Ad-IRF4 and Ad-shSRF completely reversed the IRF4-mediated neuroprotection." (PMID 24510125, 2014). "There is evidence indicating that the antiviral response to PRRSV and the IBV/PRRSV co-infection uses a combination of ISGs and IRFs such as IRF1, IRF4, and IRF7 to drive the host response." (PMID 33187194, 2020). "Notably, the salvage of neurons by the co-infection was comparable with that of AdSRF infection alone, indicating that SRF functions downstream of IRF4." (PMID 24510125, 2014).
cryptococcal infection (2 papers, 2015 to 2023). "Only mice deficient in CD11b+ conventional dendritic cells, abrogated using CD11c-cre IRF4 fl/fl mice, experienced blunted Th2 cell accumulation with cryptococcal infection." (PMID 25764512, 2015). "Therefore, our exhaustive search revealed lung-resident CDllc+ CDllb+ IRF4-dependent conventional DC (referred to as CD11b+ conventional DC) are uniquely required for Th2 cell induction in response to pulmonary cryptococcal infection." (PMID 25764512, 2015).
gastritis (2 papers, 2017 to 2020). Inflammation of the stomach. "Using logistic regression, we observed a statistically significant association between gastritis patients with metaplasia > = 10% and promoter methylation of IRF4, ELMO1 and MSC, after adjusting for age and sex." (PMID 28418867, 2017). "Promoter methylation of IRF4 (p < 0.001), ELMO1 (p < 0.001), CLIP4 (p < 0.001), and MSC (p < 0.001), is strongly associated with increasing severity of disease in the histological progression from gastritis with no metaplasia, to gastritis with metaplasia, to gastric adenocarcinoma." (PMID 28418867, 2017).
glioblastoma (2 papers, 2018 to 2024). The most malignant astrocytic tumor (WHO grade IV). "Despite the abundance of knowledge regarding TIM-3-regulated T cell immunity, very little is known regarding the potential interplay and regulation of TIM-3 by BAT3, FOXO1, BLIMP1, and IRF4 in the glioblastoma setting." (PMID 39513882, 2024). "To further validate these findings, we investigated whether changes in the percentage positivity levels of BAT3, FOXO1, BLIMP1, and IRF4 intracellular proteins are observed in T and NK cells from glioblastoma patients compared to healthy controls." (PMID 39513882, 2024). "As TIM-3 expression has been linked to BAT3, FOXO1, IRF4, and BLIMP1 activity and expression, we next explored whether the expressions of these corresponding genes correlate with one another in the glioblastoma micro-environment." (PMID 39513882, 2024).
Glucose intolerance (2 papers, 2023 to 2025). Glucose intolerance (GI) can be defined as dysglycemia that comprises both prediabetes and diabetes. "MDP supplementation reduced adipose inflammation and glucose intolerance in obese mice via nucleotide-binding oligomerization domain (NOD2) and interferon regulatory factor 4 (IRF4) independently of weight loss or changes in microbiome composition." (PMID 40508171, 2025).
Hypertension (2 papers, 2014 to 2025). The presence of chronic increased pressure in the systemic arterial system. "Interestingly, IRF4, another member of the IRF family, plays a crucial role in the pathogenesis of hypertension-induced renal inflammation and fibrosis, as demonstrated by reduced renal dysfunction and fibrotic response in IRF4 knockout mice subjected to DOCA treatment." (PMID 40332339, 2025).
immune deficiency (2 papers, 2023). "Due to this central role in T cells and similar essential functions in B cells, homozygous mutation of IRF4 causes severe immune deficiency in mice and human." (PMID 37469513, 2023). "Deficiency of IRF4 results in severe immune deficiency and affects maturation and function of most if not all T cell subsets." (PMID 37469513, 2023).
kidney injury (2 papers, 2019 to 2022). Trauma to the kidney. "Further, we have demonstrated that macrophage deletion of IRF4, a known regulator of macrophage function, ameliorates AA-induced kidney injury and subsequent chronic renal damage and fibrosis." (PMID 35025763, 2022). "We tested the hypothesis that AA directly stimulates macrophages, inducing a migratory and proinflammatory phenotype to potentiate AA-induced kidney injury, and that these effects would be reduced in mice with macrophage-specific deletion of IRF4." (PMID 35025763, 2022). "We therefore analyzed the regulation of IRF4 and selected macrophage polarity genes in patients with hypertensive nephropathy (HT), which, according to our understanding, comes closest to chronic/postischemic kidney injury." (PMID 31632388, 2019).
liver cancer (2 papers, 2021 to 2024). An epithelial or non-epithelial malignant neoplasm that arises from the liver. "Furthermore, the expression of IRF4 in PMN-MDSCs was inversely correlated with the proportion of PMN-MDSCs in liver cancer patients." (PMID 33708218, 2021).
liver fibrosis (2 papers, 2021 to 2025). "In the context of arsenite-induced liver fibrosis, histone lactylation boosts interferon-regulatory factor 4 (IRF4) expression by modifying H3K18la, promoting Th17 cell differentiation and IL-17A secretion, which activates HSCs." (PMID 40867622, 2025).
male pattern baldness (2 papers, 2017 to 2020). "Out of 13 SNPs included in our predictive models for hair greying, 6 (FGF5 rs7680591, RUNX1 rs68088846, IRF4 rs12203592, BRINP1 rs2416699, TEX41 rs10928235, GRID1 rs2814331) were previously associated with male pattern baldness (MPB)." (PMID 32758128, 2020). "A previous GWAS showed an association of IRF4 with both hair colour and hair greying, but not with male pattern baldness." (PMID 28196072, 2017).
monoclonal gammopathy of undetermined significance (2 papers, 2015 to 2017). "To evaluate the expression of IRF4 in MM patients, we analyzed public gene expression data of purified plasma cells from MM patients (n = 351) compared with normal plasma cells (NPC) (n = 22) or monoclonal gammopathy of undetermined significance (MGUS) cells (n = 44)." (PMID 29156727, 2017).
myelodysplastic syndrome (2 papers, 2021 to 2025). A clonal hematopoietic disorder characterized by dysplasia and ineffective hematopoiesis in one or more of the hematopoietic cell lines. "In delving deeper into the pathogenic mechanisms of myelodysplastic syndromes (MDS), we have observed that the pivotal gene IRF4 plays a significant role across various hematological disorders." (PMID 40073065, 2025). "Previous independent studies have unequivocally demonstrated a significant downregulation of IRF4 gene expression in myelodysplastic syndromes (MDS)." (PMID 40073065, 2025).
myeloid malignancies (2 papers, 2014 to 2025). "The lymphocyte-specific transcription factor Interferon (IFN) Regulatory Factor 4 (IRF4) is implicated in certain types of lymphoid and myeloid malignancies." (PMID 25207815, 2014).
non-Hodgkin lymphoma (2 papers, 2014 to 2020). Distinct from Hodgkin lymphoma both morphologically and biologically, non-Hodgkin lymphoma (NHL) is characterized by the absence of Reed-Sternberg cells, can occur at any age, and usually presents as a localized or generalized lymphadenopathy associated with fever and weight loss. "We have verified LIMD1 and CFLAR as two novel genes whose expression is correlated with IRF4 in non-Hodgkin lymphomas, and shown that CFLAR is likely an IRF4 target." (PMID 25207815, 2014). "Targeting CFLAR by IRF4 may implicate a role for IRF4 in Fas/TRAIL/TNFα-induced apoptosis in non-Hodgkin lymphomas." (PMID 25207815, 2014).
ovarian carcinoma (2 papers, 2020 to 2021). A malignant neoplasm originating from the surface ovarian epithelium. "IRF4, GATA4, GATA3, CIITA, and MYH11 were involved in the immune regulatory network, indicating that these five transcription factors might play a role in the immune microenvironment of ovarian cancer." (PMID 34109184, 2021).
Parkinson disease (2 papers, 2017 to 2021). A progressive degenerative disorder of the central nervous system characterized by loss of dopamine producing neurons in the substantia nigra and the presence of Lewy bodies in the substantia nigra and locus coeruleus. "Besides, pathways including Oxidative-phosphorylation, Citrate-cycle-tca-cycle, Parkinsons-disease and Huntingtons-disease were maximum extent enriched in IRF4 low expression subgroup." (PMID 34195096, 2021).
psoriasis vulgaris (2 papers, 2018 to 2021). Plaque psoriasis is the most common presentation of psoriasis. "As in other inflammatory skin conditions like psoriasis vulgaris, acne, atopic dermatitis, and hidradenitis suppurative, we found in active lesions of CLE an increased expression of IRF4 in the dermis and mTOR in the epidermis." (PMID 34944673, 2021).
rectal cancer (2 papers, 2017 to 2021). A primary or metastatic malignant neoplasm that affects the rectum. "Studies demonstrated that IRF4 was associated with rectal cancer." (PMID 33949771, 2021). "In particular, the authors demonstrated that the IRF2 mutational status is associated with both colon and rectal cancer, whereas mutations in other genes involved in IFN signaling pathway were uniquely associated with colon (IFN-γ and IRF3) or rectal cancer (IFNGR1, IFNGR2, IRF4, IRF6, and IRF8)." (PMID 28798748, 2017).
relapsing-remitting multiple sclerosis (2 papers, 2017 to 2022). The most common clinical variant of multiple sclerosis, characterized by recurrent acute exacerbations of neurologic dysfunction followed by partial or complete recovery. "Overexpressed IRF4 in naive CD4+ T cells derived from relapsing remitting multiple sclerosis patients significantly increased their ability to secrete IL-17A, IL-17F, IL-21, and IL-22." (PMID 28808358, 2017). "Silencing of IL-1R1 gene expression through small-interference RNA (siRNA) in CD4+ T cells derived from relapsing-remitting multiple sclerosis patients inhibited in vitro Th17 cell differentiation via inhibition of interferon regulatory factor 4 (IRF4) expression." (PMID 35163653, 2022).
rosacea (2 papers, 2018 to 2024). A chronic erythematous skin disorder that affects the face. "Our results show that the index SNP rs12203592 in the intronic region of the interferon regulatory factor 4 (IRF4) gene was strongly associated with rosacea symptom severity; the T allele is significantly associated with increased rosacea symptom severity (P = 1.5 × 10−17)." (PMID 29771307, 2018). "Proinflammatory cytokines and chemokines: Another GWAS study of Caucasian rosacea patients found SNP in genes such as interleukin-13 (IL-13) and interferon regulatory factor-4 (IRF4)." (PMID 39136023, 2024). "This study in individuals of 97% European ancestry has identified significant associations with rosacea genes previously implicated in skin pigmentation (HERC2-OCA2, SLC45A2, IRF4 and MC1R)." (PMID 29771307, 2018). "Collectively, the HLA, IL13 and IRF4 findings highlight the critical role of immune modulation and rosacea disease pathology." (PMID 29771307, 2018). "The associations of rosacea with the IL13, IRF4 and HLA gene regions are consistent with the known inflammatory component of the disease." (PMID 29771307, 2018). "Taken together these results indicate that rs12203592 may be impacting rosacea symptom severity through increased IRF4 expression." (PMID 29771307, 2018).
sarcoma (2 papers, 2025). A usually aggressive malignant neoplasm of the soft tissue or bone. "It has been reported that retinoic acid (RA) produced by sarcoma cells inhibits the expression of IRF4, a transcription factor that facilitates dendritic cell differentiation, thereby driving monocytes to differentiate into tumor-associated macrophages (TAMs)." (PMID 40495762, 2025).
schistosomiasis (2 papers, 2023 to 2024). An infectious disease caused by parasitic trematodes of the genus Schistosoma that colonize human blood vessels and release eggs that can cause granulomatous reactions leading to acute (swimmer's itch or acute schistosomiasis syndrome) or chronic disease. "For example, a recent study investigating pulmonary inflammation in human and murine schistosomiasis caused by S. mansoni highlighted the critical function of type 2 dendritic cells (DC2s) and their reliance on IRF4 for proper development and function." (PMID 39609883, 2024). "However, to conclusively determine the outcomes of IRF4 KO mice in schistosomiasis models infected with S. japonicum, further experimental studies are warranted." (PMID 39609883, 2024). "These cellular changes were accompanied by a significant reduction in Th2 cytokines IL-4 and IL-5 in Cre+ MGL2+ CD11b+ cDC2 depleted mice, as a proportion of CD4+ T cells, implicating Irf4-dependent dependent cDC2s as critical in promoting type-2 responses during pre-patent schistosomiasis." (PMID 37012228, 2023).
T-cell ALL (2 papers, 2013 to 2014). "In the past, however, IRF4 mRNA expression has been found low in adult samples of T-cell ALL." (PMID 23977280, 2013). "IRF4 is frequently expressed in B-cell ALL, but not in T-cell ALL." (PMID 25207815, 2014).
uveal melanoma (2 papers, 2025 to 2026). A melanoma derived from melanocytes of the uveal tract. "Single nucleotide polymorphisms (SNPs) in IRF4 and HERC2 are associated with risk for disomy or monosomy of chromosome 3 (D3 or M3) uveal melanoma (UM), respectively." (PMID 41377059, 2026). "Interestingly, both rs12203592 in IRF4 and rs12913832 in HERC2, the two most important genetic determinants of iris freckles and nevi found in this work, have also been recently identified as risk factors for developing uveal melanoma." (PMID 40261663, 2025).